NLRP3 (NLR family pyrin domain containing 3)
Diseases named in the same sentence as NLRP3 in open-access papers (continued):
Sharing a sentence is not in itself a finding about the gene and the disease.
hepatocellular carcinoma (continued). "In a preclinical model of hepatocellular carcinoma (HCC), estrogen receptor signaling increased cancer cell death through NLRP3 inflammasome-initiated, caspase-1-dependent pyroptosis and inhibition of autophagy in cancer cells." (PMID 33572196, 2021). "It was reported that NLRP3 transcription is tightly regulated by miR‐223‐3p through an evolutionarily conserved binding interaction between the 3′‐UTR of the NLRP3 mRNA and miR‐223‐3p in macrophages and hepatocellular carcinoma (HCC) cells." (PMID 33145937, 2020). "Down-regulation of the components of NLRP3 inflammasome in patients with hepatocellular carcinoma (HCC) correlates with advanced stages." (PMID 31547621, 2019). "In the present study, we demonstrate that luteoloside is a potent agent against human hepatoma cells both in vitro and in vivo, and NLRP3 inflammasome might be involved in the signaling of luteoloside-induced suppression of proliferation, migration and invasion." (PMID 24587153, 2014). "Similarly, in hepatocellular carcinoma (HCC), NLRP3 plays a protective role, as the expression of NLRP3 inflammasome partner proteins is either completely absent or significantly low in hepatic cancer cells." (PMID 40692785, 2025). "The compounds polyphyllin VI and 17β-estradiol have been shown to activate NLRP3 in cancer cells, inducing pyroptosis and improving the anti-tumoral immune response in NSCLC and hepatocellular carcinoma." (PMID 40141358, 2025). "It was also revealed in a study that miRNA-223-3p promotes apoptosis and inhibits proliferation of human hepatocellular carcinoma cells (hep3B) by regulating NLRP3, and miR-233 represses the proliferation of HCC cells and promotes apoptosis by directly targeting NLRP3." (PMID 38182564, 2024). "It is found that Stenotrophomonas maltophilia induces the formation of NLRP3 inflammasome complex by activating TLR4-mediated NF-κB signaling pathway, which drives cirrhosis to deteriorate to hepatocellular carcinoma in mice." (PMID 37370025, 2023). "The study shows that NLRP3 is upregulated in oxaliplatin‐resistant HCC cells and has a tumor‐intrinsic function in generating an immunosuppressive hepatocellular carcinoma environment by activating IL‐1β and PD‐L1 upregulation." (PMID 38116060, 2023). "In hepatocellular carcinoma (HCC) cells, for example, pyroptosis induction through NLRP3 inflammasome activation significantly impeded metastatic potential in vitro and tumor growth in vivo in a mouse xenograft model." (PMID 34429144, 2021). "Resaerchers have reported that luteoloside suppresses hepatocellular carcinoma cells (HCC) through the inhibition of HCC migration and invasion and has the capacity to downregulate the expression level of NLRP3, caspase-1 and IL-1β, suppressing proliferation and metastasis of HCC." (PMID 32650482, 2020). "In addition to priming tumoricidal activity of hepatic NK cell, NLRP3 inflammasome also induces caspase-1-mediated pyroptosis to control the proliferation of hepatocellular carcinoma (HCC) cells." (PMID 30319645, 2018). "The relevant studies have reported that NLRP3 inflammasome upregulates the expression of PD-L1 in patients with diffuse large B-cell lymphoma, and IRF1 promoted the expression of PD-L1 in hepatoma cells." (PMID 37325556, 2023). "The expression of NLRP3 decreased or was even lost in hepatocellular carcinoma (HCC), which is related to poorer pathological differentiation and advanced stage, suggesting that the gene may be a tumor suppressor gene in HCC." (PMID 34805183, 2021). "The NLRP3 activation induced by HCV promotes chronic intrahepatic inflammation in macrophages and interrupts cellular lipid metabolism in HCV-infected hepatoma cells, both of which contribute to chronic liver injury and liver disease progression." (PMID 29163496, 2017). "However, Whether NLRP3 inflammasome plays an important role in the process of hepatocellular carcinoma (HCC) is still unknown." (PMID 24587153, 2014).
hepatocellular carcinoma (continued). "Pyroptosis could be a protective factor for hepatocellular carcinoma, in which the expression of NLRP3, a pyroptosis-related protein, had a negative relationship with the clinical stage and pathologic grade." (PMID 37305457, 2023). "In hepatocellular carcinoma (HCC), significant downregulation of NLR family pyrin domain containing 3 (NLRP3) was observed, which was inversely correlated with clinical stage." (PMID 34925457, 2021). "This was demonstrated using the diethylnitrosamine (DEN) mouse model of hepatocellular carcinoma (HCC), in which the mitophagy effector FUNDC1 was specifically deleted in hepatocytes leading to aberrant activation of the Nlrp3 inflammasome and IL-1β-driven hepatocyte hyperproliferation." (PMID 35517498, 2022). "Furthermore, it has been reported that NLRP3 inflammasome components, including NLRP3, ASC, and procaspase-1, are downregulated in hepatocellular carcinoma (HCC)." (PMID 25941664, 2015). "In human hepatocellular carcinoma (HCC), components of the NLRP3 inflammasome were found to be either absent or else significantly downregulated." (PMID 37289257, 2023).
hyperuricemia (90 papers, 2012 to 2026). An abnormally high level of uric acid. "Research has demonstrated that certain agents can effectively decrease UA production to mitigate liver damage associated with hyperuricemia through regulating the oxidative stress levels and the NLRP3 pathway." (PMID 40365321, 2025). "In this study, L. reuteri Urob-7 effectively suppresses the NLRP3 inflammasome pathway, thereby mitigating inflammation associated with hyperuricemia." (PMID 41227678, 2025). "Recently, ROS/NLRP3 inflammasome-mediated endothelial cell pyroptosis has been reported as the critical mechanism underlying the relationship between hyperuricemia and atherosclerosis." (PMID 38548844, 2024). "The NLRP3 inflammasome, which recognizes uric acid salts, is involved in the inflammatory response associated with hyperuricemia." (PMID 39599650, 2024). "The TLR4/MyD88/NF-κB and NLRP3 proteins are reported to be the major signalling pathways closely associated with renal inflammation caused by hyperuricemia." (PMID 36839325, 2023). "The NOD-like receptor 3 (NLRP3) mediated inflammation is closely associated with the pathogenesis of various forms of renal disorders and their complications, including hyperuricemia." (PMID 33959014, 2021). "In this study, we demonstrated that hyperuricemia can cause intrarenal crystal formation in the kidney, macrophage infiltration, and upregulation of NLRP3 and IL-1β expression." (PMID 33648977, 2021). "This consequently regulates the renal organic ion transporter expression, suppresses renal NLRP3 inflammasome activation, and provides the evidence for its use in the treatment of hyperuricemia and its associated kidney inflammation." (PMID 31915448, 2019). "Hyperuricemia not only reflects abnormal purine metabolism but also exacerbates local inflammatory responses by activating the NOD-like receptor thermal protein domain associated protein 3 (NLRP3) inflammasome within the kidney through crystal deposition." (PMID 41844384, 2025). "Therefore, targeted drug research focusing on TLR4 and the NLRP3 inflammasome is vital for addressing the complications associated with hyperuricaemia." (PMID 38041694, 2023). "Whether it can cause mitochondrial autophagy and further activate the NLRP3 inflammasome under the condition of hyperuricemia remains to be further elucidated." (PMID 35382689, 2022). "Other studies have also found that TLRs/NF-κB signaling pathway and NLRP3 inflammatory body activation may lead to IL-1β–driven inflammatory response, causing hyperuricemia in kidney injury." (PMID 32089717, 2020). "Inhibiting the expression of NLRP3 inflammasome-related pathway proteins can effectively alleviate the uric acid nephropathy resulting from elevated uric acid levels and is a feasible strategy in preventing and treating the uric acid nephropathy caused by hyperuricemia." (PMID 38257077, 2024). "One mechanism of renal impairment induced by hyperuricemia is due to the effect of monosodium urate monohydrate crystals in the kidneys, as well as in joints and other organs, which activate the NLRP3 inflammasome cascade and lead to interleukin-1β activation." (PMID 39937787, 2025). "Hyperuricemia amplifies these processes: xanthine oxidase-derived reactive oxygen species, reduced nitric-oxide bioavailability, and, to a larger extent, NLRP3 inflammasome activation (IL-1β/IL-18) allow for near-constant “inflammatory priming”." (PMID 41515581, 2025). "This inhibition of NLRP3 inflammasome activation by SMM ameliorated hyperuricemia, renal dysfunction, and renal histopathological changes induced by PO." (PMID 40841164, 2025). "Shizhifang inhibits hyperuricemia-induced renal tubular epithelial cell pyroptosis through targeting NLRP3 to induce tubular inflammation." (PMID 40305201, 2025). "In the context of hyperuricemia, the NLRP3 inflammasome is often activated in mice due to the presence of uric acid crystals, which the immune system recognizes as a danger signal." (PMID 41009565, 2025).
hyperuricemia (continued). "Hyperuricemia promotes the release of proinflammatory cytokines such as IL-1β by activating the NLRP3 inflammasome, leading to atrial fibrosis and structural remodeling." (PMID 40469443, 2025). "Spinasterol alleviates hyperuricemia-induced renal tubular inflammatory injury and improves renal excretory function by inhibiting NLRP3 inflammasome activation." (PMID 41009565, 2025). "By simultaneously targeting hyperuricemia and the NLRP3-mediated inflammatory cascade, this dual approach attenuates acute inflammatory responses and preserves joint and renal integrity." (PMID 40430581, 2025). "Hyperuricemia‐induced autophagy and NLRP3‐dependent inflammation are critically involved in the development of renal damage." (PMID 39438268, 2024). "This study revealed a significant upregulation of NLRP3 inflammasome pathway-related proteins in the kidney tissues of hyperuricemia mice." (PMID 38257077, 2024). "Given that TLR4 and the NLRP3 inflammasome play a significant role in hyperuricaemia-related kidney injury, recent scientific efforts have been focusing on the development of drugs that specifically inhibit TLR4 and the NLRP3 inflammasome." (PMID 38041694, 2023). "For example, a study reported that hyperuricemia resulted in kidney damage via inducing autophagy and NLRP3-mediated inflammation." (PMID 37138053, 2023). "Thereby, inhibition of the NLRP3 inflammasome is a practicable strategy to alleviate side effects of hyperuricemia." (PMID 37124197, 2023). "In this study, we found that NLRP3, cleaved caspase-1 were increased in the heart tissue of hyperuricemia mice." (PMID 36986461, 2023). "Expression of XOD and proteins associated with NLRP3 inflammasome signaling, such as TLR4, NF-κB, NLRP3 and IL-18, was increased in the liver tissues of mice suffering from hyperuricemia induced by yeast extract compared with those in the normal group." (PMID 37124197, 2023). "Despite the wealth of information supporting the contribution of TLR4 and the NLRP3 inflammasome to the pathophysiology of hyperuricaemia nephropathy, clinical application of therapies targeting these pathways remains unachieved." (PMID 38041694, 2023). "NLRP3 inflammasome activation has been proved to play an essential role in the development of cardiac damage induced by hyperuricemia." (PMID 36986461, 2023). "In animal studies, compounds and molecules that disrupt the mechanisms of NLRP3 inflammasome and TLR4 activation have been shown to decrease the production of these mediators, thereby attenuating renal damage caused by hyperuricaemia." (PMID 38041694, 2023). "In conclusion, we provided evidence that the synergistic effect of ATP on MSU crystal-induced NLRP3 inflammasome activation is required for AGA development in rats in the context of hyperuricemia." (PMID 36686377, 2023). "Understanding these aspects will provide new insights into the mechanisms of renal damage in hyperuricaemia and enhance our comprehension of TLR4 and NLRP3’s roles in hyperuricaemia nephropathy." (PMID 38041694, 2023). "In recent years, studies have found that hyperuricemia or uric acid crystals can activate NLRP3 inflammasomes, and the activation of NLRP3 inflammasomes plays an important role in kidney disease." (PMID 35382689, 2022). "The NLRP3 inflammasome is activated by hyperuricemia and responds to DAMPs (including ROS, ATP, extracellular matrix components and crystalline substances) released from damaged kidney tissue." (PMID 35382689, 2022). "In this review, we have shown the mechanisms by which some natural bioactive compounds suppress activation of the NLRP3 inflammasome in mice with hyperuricemia." (PMID 36483739, 2022). "Phloretin has been shown to effectively attenuate urate-induced renal injury by inhibiting Nlrp3 and urate reabsorption mediated by Glut9 and promoting urinary urate excretion in mice with PO-/adenine-induced hyperuricemia." (PMID 36483739, 2022).
hyperuricemia (continued). "The protein expression of NLRP3, ASC, and Caspase-1 in the kidney tissue of hyperuricemia mice and the level of mice inflammatory cytokines NLRP3 and IL-1β was significantly reduced; this change was demonstrated at each dose in the dosing groups." (PMID 36120294, 2022). "The anti-inflammasome activity of pterostilbene in hyperuricemia model has been demonstrated by an in vitro assay where NLRP3 inflammasome and epithelial–mesenchymal transition in renal cells have been stimulated by TGF-β." (PMID 35276849, 2022). "In a rat study, treatment with 10% Fru for 6 weeks induced hyperuricemia, IR, and renal inflammation via activation of the NLRP3 inflammasome and the TLR4–MyD88 signaling pathway." (PMID 35495917, 2022). "The levels of NLRP3 and IL-1β inflammatory factors in serum and kidney of hyperuricemia mice also increased significantly." (PMID 36120294, 2022). "Another interesting aspect of uric acid and hyperuricaemia is the role of urate as an activator of the NLRP3 inflammasome, and thereby of IL-1β production." (PMID 33748660, 2021). "The activation of NLRP3 inflammasome has been proved to be a target of hyperuricemia induced renal injury." (PMID 34305953, 2021). "By using this model, we demonstrated that hyperuricemia induces renal damage together with tubular injury and kidney fibrosis through activation of autophagy and NLRP3 inflammasome-mediated inflammation." (PMID 33648977, 2021). "A large number of natural extracts have been found to improve renal function by inhibiting the activity of NLRP3 inflammasome in hyperuricemia." (PMID 34305953, 2021). "Phloretin can reduce hyperuricemia-induced renal inflammation, fibrosis, and mitochondrial stress in mice by co-inhibiting NLRP3 inflammasome activation and uric acid reabsorption." (PMID 33390969, 2020). "The pro-inflammatory role of hyperuricemia provides the rationale for targeting NLRP3 and IL-1β as a potential disease-modifying therapy for neurological disorders." (PMID 24511458, 2013). "Emerging evidence underscores the centrality of FA metabolism perturbations in driving disease progression, from hyperuricemia-triggered crystal deposition to sustained NLRP3 inflammasome activation, ultimately forming a self-perpetuating “metabolism-immunity” axis." (PMID 41181107, 2025). "The association between hyperuricemia and NAFLD severity may be mediated by NLRP3 inflammasome activation." (PMID 40224639, 2025). "Preclinical evidence suggests that hyperuricemia may exacerbate RA autoimmune pathogenesis through dual mechanisms: crystal-dependent NLRP3 inflammasome activation and crystal-independent enhancement of Th17 differentiation." (PMID 40837562, 2025). "Tuna oligopeptides ameliorate hyperuricemia and GA by reprogramming UA metabolic pathways, inhibiting NLRP3 inflammasome and TLR4/myeloid differentiation primary response 88/nuclear factor-kappa beta signaling pathway activation, and p65-nuclear factor-kappa beta phosphorylation." (PMID 40607437, 2025). "Sea cucumber oligopeptides significantly alleviate hyperuricemia, with action mechanisms encompassing UA metabolism modulation, NLRP3 inflammasome and nuclear factor-kappa beta-related signaling pathway activation inhibition, and m6A methylation level restoration." (PMID 40607437, 2025). "However, chronic hyperuricemia can activate NLRP3 inflammasome, promote macrophage infiltration and IL-1β release in adipose tissue, and induce adipocyte hypertrophy and fibrosis." (PMID 40376050, 2025). "The molecular mechanism of its specific action may be related to the inhibition of the TLR4/MyD88 signaling pathway and the NLRP3 inflammasome activation, thereby reducing IL-1β production in high fructose-induced hyperuricaemia mice." (PMID 38041694, 2023).